TNF (tumor necrosis factor)
Diseases named in the same sentence as TNF in open-access papers (continued):
Sharing a sentence is not in itself a finding about the gene and the disease.
cancer (continued). "Pro-inflammatory mediators, such as TNF-α, IL-6, IL-1B, and MCP-1, are involved in the secondary activation of many genes involved in the pathogenesis of inflammation and cancer." (PMID 37103287, 2023). "Adipocytes secrete many adipokines, cytokines, and chemokines (i.e., IL-1b, TNF-α, IL-6, TGF-β) that affect inflammation and fibrosis which promote cancer development." (PMID 37491420, 2023). "In patients with active cancer, the PFS in patients exposed to TNFi was similar to the PFS of patients exposed to non-TNFα biologics (HR = 0.76; 95% CI, 0.25–2.30; p = 0.62)." (PMID 37568640, 2023). "Secreted inflammatory cytokines in cancer cells, including IL-22, IL-6, IL-8, IL-4, IL-1β, HGF, IGF-1, EGF, G-CSF, TNF-α, VEGF, and IL-11, can confer the promotion of chemo- and radioresistance." (PMID 38140352, 2023). "Several pro-inflammatory cytokines, such as TNF-α, IFN-γ, IL-1, IL-2, IL-6, and IL-12, have been identified to participate in both initiation and progression of cancer." (PMID 37296375, 2023). "Consequently, TNFα may increase the proliferation and metastatic potential of cancer cells." (PMID 36900285, 2023). "The cGAMP pathway refers to the transfer of cGAMP from cancer cells to astrocytes through gap junctions, stimulating astrocytes to express interferon (IFN) and tumor necrosis factor alpha (TNF-α)." (PMID 37056723, 2023). "Like PB-NK cells, iPSC-derived NK (iNK) cells also exhibit cytotoxicity against diverse cancer cells via releasing perforins and granzymes, producing proinflammatory IFN-γ and TNFα, and inducing apoptosis through TRAIL and Fas-FasL interaction." (PMID 37316891, 2023). "The results of this study show that The active components of the A. cantoniensis Hance can affect cancer signaling pathway, endocrine resistance, PI3K-AKt signaling pathway, MAPK signaling pathway, IL-2/IL-6/IL-17 signaling pathway and TNF signaling pathway." (PMID 37035802, 2023). "Taken together, these results demonstrate the potential for combined IAP and WEE1 inhibition to exert anti-cancer activity and sensitize HNSCC cells to TNFα-induced cytotoxicity." (PMID 36831373, 2023). "IL-6, IL-17, TNF-α, TLR-2, and TLR-4 were significantly more highly expressed in the cancer tissues (p < 0.05)." (PMID 38075864, 2023). "In that study, we induced EMT in the cancer cell lines via treatment with TGF β1, EGF, or TNF-α for up to 7 days with analysis conducted using single-cell RNA-sequencing." (PMID 38067396, 2023). "Elevated TNF-α serum levels have been shown in anti-TIF1-γ antibody-positive DM patients suffering from significant muscle weakness and elevated cancer rate." (PMID 36357631, 2023). "Functions of certain cytokines are explored; CCA and cancer stromal cells secrete inflammatory cytokines, such as IL-1, IL-6, IL-8, IL-10, TNF-α, and TGF-β, to promote cancer growth, metastasis, and immune evasion." (PMID 36883059, 2023). "Related studies have shown that TNF-α derived from M2-TAM can promote Epithelial mesenchymal transformation (EMT) and cancer stemness." (PMID 37316699, 2023). "When tofacitinib was compared to tumor necrosis factor (TNF) inhibitors, the overall cancer RR was 1.40 (95% CI, 1.06–2.08; p = 0.02)." (PMID 37190126, 2023). "These infiltrating immune cells can stimulate tumor necrosis factor (TNF), IFN, matrix metalloproteinases, natural killer (NK) cells, and T cells, leading to the destruction of cancer cells." (PMID 37513835, 2023). "The present study identified VEGF-A, TNF-α, CCL2, IL-6, and IFN-γ as significant potential biomarkers indicating the presence of cancer and demonstrated a more detailed cytokine profile during diagnosis." (PMID 36357631, 2023). "Based on DEGs between low-high radiomics score groups, some pathways in cancer, such as HIF-1 signaling pathways and TNF signaling pathways, were significantly enriched." (PMID 37188171, 2023).
cancer (continued). "Globally, in this study, they observed a comparable use of anti-TNFα but a lower use of IMM (19 vs. 25%, p < 0.001) in patients with cancer vs. controls." (PMID 36672491, 2023). "EphrinA2 was also found to confer resistance to tumor necrosis factor alpha (TNF-α)-induced apoptosis, thus promoting cancer cell survival." (PMID 37444544, 2023). "The cross-talk between cancer cells and the components of TME mediated by TGF-β, TNF-α, TNF-β and NF-kB signaling contribute to cancer progression." (PMID 36674635, 2023). "TNFα mediates TNFR1-dependent IL-17 production by CD4+ T cells and can promote the activities of immune and cancer cells within tumors." (PMID 36835413, 2023). "The ANO1 channel (TMEM16A) is involved in cancer cell proliferation, invasion, survival, and apoptosis; the signaling pathways that can be regulated by ANO1 include ERK, PI3K-Akt, TNF, Ca-M, and EGFR." (PMID 37408210, 2023). "We also unveil the role of a poorly characterized cancer-testis antigen, Adam2, in establishing a cold TME by blocking type I and II interferon and TNFα pathways." (PMID 37258521, 2023). "Peripheral blood monocyte TNF secretion inversely correlates with the degree of dysplasia in IPMN and cancer stage in PDAC, suggesting innate immune reprogramming as IPMNs progress to invasive disease." (PMID 37575220, 2023). "Cytotoxins (perforin and granzyme) and cytokines (TNF-α and IFN-γ) were dramatically released from the BsAb-armed T cells after engaging cancer cells, resulting in a remarkable anti-cancer efficacy." (PMID 37259079, 2023). "A significant positive correlation was observed between the LDH levels and the inflammatory cytokines VEGF-A, TNF-α, CCL2, and IL-6 levels within the Cancer TIF1-γ-DM group." (PMID 36357631, 2023). "At the molecular level, RT-qPCR was used to assess gene expression of CASP8, TNF-α, and IL-6 genes in Caco-2 and COLO-205 cancer cells." (PMID 36770882, 2023). "Instead, STMN1 and the microtubule-associated kinase WNK1 are also involved in cell cycle control, cell survival and apoptosis, as components of diverse cancer signaling networks including PI3K/AKT, TNF and NF-κB signaling." (PMID 37305581, 2023). "T cell exhaustion is a state of T cell dysfunction that occurs during many chronic infections and cancers; during this process CD8 T cell-TNF (effector CD8 T cells) gradually transform into CD8 T cell-LAG3 (exhausted CD8 T cell) from HBV cirrhosis to HBV HCC." (PMID 38116005, 2023). "The identification of neutrophils as a significant source of TNF in human and murine PDAC is a critical discovery that sheds new light on the intricate interplay between the immune system and cancer." (PMID 37455286, 2023). "The KEGG study resulted mainly in cytokine receptor and IL-17 signaling route; cancer-related signaling pathways including NF-kappa B, TGF-β, TNF, PI3K-Akt; and the viral carcinogenesis signaling pathway." (PMID 37893009, 2023). "Oncogenic pathways (PI3K-Akt, IL-17, NF-ΚB, TNF, AMPK, focal adhesion, pathways in cancer, etc.)were notably enriched, suggesting the IRscore was linked with post-transcriptional events as well as regulation of oncogenic pathways." (PMID 37885006, 2023). "Numerous inflammatory cytokines, such as TNF, PGE2, IL-1, IL-6, and IL-1, have been reported to have a direct effect on the levels and activity of GPX4 in cancer cells." (PMID 37598126, 2023). "This interaction results in the expansion and activation of effector T cells, responsible for the direct or indirect killing of cancer cells, primarily through cytokine production such as Interferon gamma (IFN-γ) and tumor necrosis factor alpha (TNF-α)." (PMID 37516849, 2023). "Pentamidine enhanced T-cell-mediated cytotoxicity against various cancer cells in vitro by increasing the secretion of IFN-γ, TNF-α, perforin, and granzyme B in the culture medium." (PMID 37205112, 2023).
cancer (continued). "These include its role in combating lipoperoxidation, decreasing neurogenic pain, and reducing tumor necrosis factor (TNF) levels, which hold significance in conditions like cancer." (PMID 37520490, 2023). "APOA mimetic peptide 4F (L-4F) exerts an anti-inflammatory effect by reducing levels of tumor necrosis factor (TNF-α) and interleukin-6, which have been shown to Inhibit cancer development both in vitro and in vivo." (PMID 38067270, 2023). "Our findings revealed that NF-κB p65 (RelA) expression levels were comparatively higher in GBM than in other tumors, while TNFα showed differential expression in GBM and other cancers through bioinformatics analysis." (PMID 37892820, 2023). "The products of TNF and TNFSF10 can be inhibited by binding to decoy receptors such as cFLIP, which are overexpressed in several cancer types and aid cell proliferation, growth and survival." (PMID 36679328, 2023). "Major pathways include pathways in cancer, PI3K-Akt pathway, TNF pathway, apoptosis pathway, mTOR pathway, etc." (PMID 38065884, 2023). "It has been reported that TNF-α and TGF-β1 play a crucial role in cancer initiation, proliferation, progression, metastasis, and EMT induction by facilitating the loss of epithelial proteins and increasing the upregulation of mesenchymal proteins." (PMID 37445768, 2023). "There is evidence suggesting that urinary IL-2 levels as well as IL-6, IL-8, IL-12, TNF-α, and IFN-γ are promising markers in predicting BCG clinical responses suggesting cytokines as a potential treatment for cancer." (PMID 37588093, 2023). "CTLs directly destroy cancer cells by releasing cytotoxic granules, such as GrB, and secrete cytokines, primarily IFN-γ and TNF-α, which possess antitumor effects." (PMID 35873573, 2022). "Additionally, TNF could influence tumorigenesis and cancer progression via TME regulation." (PMID 36505472, 2022). "TAMs have been reported to support invasion and metastasis by secreting EGF1 and TNFα, which promote EMT and enhance the stemness and angiogenesis of cancers." (PMID 36531496, 2022). "KEGG pathway enrichment analysis identified nine overlapping pathways, which were involved in cancer, cellular community, cardiovascular disease, and immune regulation and directly acting on PI3K/AKT and TNF pathways." (PMID 36139627, 2022). "TNFα can have both pro- and antitumorigenic effects based on interaction with its receptors TNFR1 and TNFR2 in cancer." (PMID 35859928, 2022). "Although its role in cancer remains controversial (as previously explained), TNF-α has been shown to play a key role in the pathogenesis of NHL and may increase the risk of disease together with leptin, especially in FL and DLBCL, through polymorphisms in the TNF rs1800629G>A gene." (PMID 36555171, 2022). "Combination cancer therapy with KD showed decreased expression of COX-2 and pro-inflammatory cytokines, such as tumor necrosis factor-α (TNF-α), interferon-γ (IFN-γ), and ILs including IL-1β) via inhibition of NF-κB." (PMID 36432618, 2022). "Furthermore, a recent population-based cohort study in Denmark on more than 56,000 inflammatory bowel disease patients reported that there is no significant risk of cancer when treated with TNF-α antagonists such as infliximab, adalimumab, and certolizumab pegol." (PMID 35954156, 2022). "Many proinflammatory cytokines, such as Tumor Necrosis Factor (TNF-α) and interleukins, have been shown to promote the initiation of tumorigenesis in various cancers through aberrant expression of miRNAs." (PMID 36189271, 2022). "In the stepwise part of cancer antigen presentation, NK cell-derived IFN-γ and TNF-α are proved to promote the activation and maturation of DCs and macrophages, which enhance the strength of antigen presentation." (PMID 35803912, 2022).
cancer (continued). "By contrast, the tumor necrosis factor (TNF)-α is also secreted by adipose tissues, and its levels correlate with the degree of adiposity, but its role in cancer remains controversial." (PMID 36555171, 2022). "Copper chelator downregulates PD-L1 expression by inhibiting the response of cancer cells to proinflammatory cytokines such as IFN-γ, TNF-α and TNF-α/β." (PMID 35279217, 2022). "In inflammation, dendritic cells can start producing TNF and nitric oxide (NO), which is essential for CD8-positive T cells to perform an anti-cancer function." (PMID 35741450, 2022). "An exception is those cancers expressing low levels of IAP proteins, for example, MCF7 cells, whose growth can be directly inhibited by TNFα." (PMID 36119107, 2022). "The main pro‐inflammatory signal proteins secreted from the cancer cells include VEGF‐A, transforming growth factor β (TGFβ), and tumor necrosis factor (TNF)." (PMID 35506376, 2022). "In cancer colonocytes, the activation of pro-inflammatory genes was not so evident compared to the healthy ones, but elevated levels of TLR4, IL1R1 and TNFα in some bacteria- and bacteria with hPA120-treated HCT116 cells were found." (PMID 36296918, 2022). "PD-L1 is upregulated on the surface of many types of cancer cells by IFN-γ and TNF-α, and the regulation involves some endogenous carcinogenic pathways (e.g., the PI3K-AKT and AMPK pathways)." (PMID 35279217, 2022). "The KEGG analysis results showed that S. officinalis significantly influenced the pathways in cancer, such as PI3K–Akt, HIF-1, TNF, IL-17, Ras signaling pathways, etc.." (PMID 35646655, 2022). "Equally interesting, tumor necrosis factor (TNF)-α, an inflammatory mediator, promotes cancer cell proliferation and malignant transformation by regulating other molecules." (PMID 36235818, 2022). "The top 16 pathways included cancer, metabolism, PI3K-Akt, MAPK, TNF, RAS, Fox0, HIF-1, thyroid hormone signalling pathway, focal adhesion, and HTLV-I infection pathways." (PMID 36102631, 2022). "The death ligand tumor necrosis factor (TNF)-related apoptosis-inducing ligand (TRAIL), a member of the TNF cytokine superfamily, has long been recognized for its potential as a cancer therapeutic due to its low toxicity against normal cells." (PMID 36291908, 2022). "TNF-α has been reported to be a bona fide agonist of MAP4K4, and TNF-α is known to induce inflammation and cancer." (PMID 36292671, 2022). "TNF-α secreted by macrophages promotes the expression of CXCL1, which is involved in cancer development and malignant progression." (PMID 36552865, 2022). "The reason why ADP@SWNT/TNFα exhibited an obvious inhibitory effect was due to the SWNT‐induced penetration effect, which inhibited the proliferation of cancer cells." (PMID 34994069, 2022). "Collectively, these findings support that ICC/IDC cancer cells have high inter-patient heterogeneity, but commonly upregulate SCHLAP1 and TNFα signaling via NFĸB pathway member JAG1." (PMID 36229464, 2022). "The treatment with the TNF-α neutralizing antibody in the CM of WT BMDMs and KLK6-overexpressing RAW 264.7 cells suppressed CXCL1 production from cancer cells." (PMID 36552865, 2022). "Chanling Gao exerted the analgesic effects in the cancer-induced bone pain (CIBP) rat model by inhibiting the IKKβ/NF-κB signaling pathway and the synthesis and release of TNF-α, IL-1β, and IL6." (PMID 36415861, 2022). "Activated NK cells act on cancer via various pathways mainly through the cytotoxicity pathway and production of cytokines IFN-γ and TNF-α." (PMID 36102418, 2022). "Epidermal growth factor (EGF), tumor necrosis factor-α (TNF-α), and Wnt signals are reported to cooperate with TGF-β signaling during cancer progression." (PMID 36140527, 2022). "At the promotion stage, inflammatory cytokines (notably TNF, IL-1β and IL-6) induce NF-κB and STAT3 transcription factors in cancer cells, which activate genes controlling cell survival, proliferation and growth." (PMID 35406394, 2022).
cancer (continued). "TNF-α-induced expression of MMP-9 was involved in macrophage fusion and human M13SV1-EGFP-Neo breast epithelial cells × human MDA-MB-435 cancer cell hybridization." (PMID 36555709, 2022). "Among these signatures (TNF, TIRAP, CASP9, PLCG1, PRKACA, CASP3, CASP8, CASP4), TNF (Tumor necrosis factor) is currently considered a two-edged sword in cancer development." (PMID 35741587, 2022). "This abnormal myelopoiesis in cancer and chronic inflammation is induced by several cytokines, including interleukin (IL)-17A, G-CSF, GM-CSF, and TNF (tumor necrosis factor)-α, as well as transcription factor ROR1C." (PMID 36395389, 2022). "KEGG pathway enrichment analysis showed that SHD has a therapeutic effect on IS through regulatory pathways (such as endocrine resistance signaling pathway, estrogen signaling pathway, TNF signaling pathway, AGEs/RAGE signaling pathway, and miRNAs in cancer)." (PMID 35097126, 2022). "Inflammatory mediators such as IL-1, IL-6, TNF-α, and IFN-γ are generated in cancer cachexia, resulting in increased energy expenditure, decreased appetite, and muscular atrophy." (PMID 35159388, 2022). "In this study, we analyzed the associations of interleukins (IL) 1β, 2, 4, 5, 6, 8, 10, 12p70, 17, IFN-γ, TNF-α, and IFN-α and blood routine indexes with the demographic and clinical characteristics of 134 cancer patients." (PMID 36157224, 2022). "Because osteopontin (OPN), IL‐1β, tumor necrosis factor (TNF)‐α, and IL‐6 are well‐known growth factors derived from macrophages, cancer cells were stimulated with these recombinant proteins, and cell proliferation was assessed with the WST assay." (PMID 35132816, 2022). "In comparison, FADD in 12 cancer types, FASLG in 3 cancer types, RIPK1 in 19 cancer types, TLR3 in 25 cancer types, TNF in 11 cancer types, FAS in 22 cancer types, MLKL in 15 cancer types, and RIPK3 in 12 cancer types had homozygous deletions." (PMID 35748782, 2022). "Molecular docking of compounds 4 and 6, the cancer-inducing agent NDEA, and the standard sorafenib was performed on the targeted proteins, namely MDM2, TNF-α, TGF-β, FAK, and IL-6." (PMID 35661799, 2022). "TRAF4 significantly enhances cancer development and progression in various malignancies, and its effects involve multiple signaling pathways such as AKT, NF-κB, Wnt, TGF-βand TNF-α." (PMID 35242717, 2022). "In cancer, NLRX1 has been shown to downregulate key cytokines that are important in cancer progression, such as tumor necrosis factor (TNF) and interleukin (IL)-6." (PMID 34697412, 2022). "Thus, in the presence of TAPI-0, the down-regulation of cell-derived sTNFR1 and sTNFR2 (and possibly also higher levels of TNFR1/TNFR2 left on the cell membrane) may stand in the basis of the increased ability of TNFα to induce the production of the pro-metastatic chemokines by the cancer cells." (PMID 35884574, 2022). "Significant overlap existed at sites for AR binding at AREs, FOXA1 motifs, and sites that regulate key cancer pathways, including WNT, TGFβ, PI3K, MAPK, Hippo signaling, TNFα, and epithelial-to-mesenchymal transformation." (PMID 35650195, 2022). "These immune cells, as anti-cancer immune cells, release cytokines such as interferon-gamma (IFN-γ) and tumor necrosis factor (TNF)-alpha which are major effectors upregulating HLA class I molecules." (PMID 36437379, 2022). "CD8+ T cells are known to be crucial members of the adaptive immune response to defend against intracellular pathogens and cancer cells by producing IFN-γ, TNF and cytotoxic molecules such as perforin and granzymes." (PMID 35205732, 2022). "The antitumor effects of human TNF-α protein on Caco-2, HepG-2 and MCF-7 cancer cell lines were investigated concerning the morphological shape of cells by fluorescence microscopy using an EtBr and AO dye mix." (PMID 35205024, 2022).